KRAS (KRas proto-oncogene, GTPase)
Diseases named in the same sentence as KRAS in open-access papers (continued):
Sharing a sentence is not in itself a finding about the gene and the disease.
tumor (continued). "Combination treatment also reduced tumor growth in KRAS-mutant xenograft tumors dependent on SVCT2 levels; intracellular or tumor ascorbate levels have again not been measured." (PMID 28484682, 2017). "Moreover, the c-MET amplification locus could be detected in circulating tumor DNA, suggesting that the early initiation of c-MET inhibitors in those patients who respond to anti-EGFR therapies and do not display emergence of KRAS mutations in blood tests during anti-EGFR therapies." (PMID 28368335, 2017). "Since the PDHK4 expression is not high in these tumour cells, we studied the effect of full-length PDHK4 over-expression on KRAS, pERK and pPDH levels." (PMID 28692044, 2017). "No other significant correlations between KRAS or NRAS mRNA expression and gender, AJCC stage, tumor thickness, or ulceration were found." (PMID 29349077, 2017). "CDK1 was validated using a different KRAS isogenic cell model (SW48) as well as a series of non-isogenic CRC and PDAC tumour cell models." (PMID 26881434, 2016). "A sole mutant KRAS A549 cell line had increased colony formation in response to OTUB1 overexpression; however, in vivo tumor growth of A549 was not affected upon OTUB1 overexpression." (PMID 26881969, 2016). "We found the extent of CDK1 phosphorylation at Thr161 to be enhanced in KRAS mutant cells compared to WT cells in the SW48 KRAS isogenic model, PDAC and CRC non-isogenic tumour cell lines." (PMID 26881434, 2016). "Expression of let-7 suppressed KRAS expression and mitogen-activated protein kinase activation (MAPK), and inhibited cell proliferation but failed to hinder tumor progression." (PMID 27322337, 2016). "When tumor cells are exposed to cetuximab, expression of TIMP-1 will be inhibited, irrespective of KRAS status." (PMID 27509063, 2016). "This indicates that the individual MMP/TIMP composition at the leading edge of each tumor might create a fine-tuned microenvironment irrespective of (and of higher prognostic relevance than) expression of one MMP or baseline oncogenic mutations, such as KRAS or BRAF." (PMID 26106602, 2015). "Of those specialists in France who did not test KRAS status, reasons for not testing were that the patient had received prior anti-EGFR-treatment (63% of patients) or there was an absence of tumor/technical issues (27% of patients)." (PMID 26491871, 2015). "We further demonstrate that inhibition of KRAS signaling alone via co-targeting the MAPK and PI3K pathways fails to induce extensive tumor cell death and, therefore, has limited efficacy against PDAC." (PMID 26158412, 2015). "In patients with a KRAS wild type tumor, the median PFS was 10.3 vs. 11.4 months (p = 0.882) for nonusers compared to statin users, and in the KRAS mutant group 7.6 vs. 6.2 months (p = 0.291), respectively." (PMID 25375154, 2014). "We assessed the median size of the tumors and the distribution of tumor sizes were compared using a two-tailed Mann-Whitney U test between the LEX-EGFP-iCL negative control and the five conditions where KRAS is present." (PMID 24489653, 2014). "Oncogenic KRAS activates SHH production, but HH ligands do not activate the HH pathway in tumor epithelial cells in an autocrine manner (Lauthet al., 2010;Millset al., 2013;Yauchet al., 2008)." (PMID 25352983, 2014). "The IC50 values for P7170 were in the broad range of 3 to 300 nM independent of either the genetic status of KRAS, PIK3CA, PTEN or the tumor sub-types." (PMID 25466244, 2014). "As samples from the AIO KRK-0104 trial were only tested for KRAS exon 2 codon 12/13 mutations, but not for KRAS exon 3, 4 or NRAS mutations, our data might contain a bias of approximately 10 % hidden mutations that we cannot identify due to lacking tumor material." (PMID 24816724, 2014).
tumor (continued). "We performed 658 assays by PNA-PCR and direct sequencing and found a significantly higher percentage of KRAS gene alterations with PNA-PCR (41% vs. 30%; p < 0.001), which was independent of the sample source (FFPE tumor samples or frozen plasma)." (PMID 25491325, 2014). "So far KRAS is the only potential biomarker for predicting the efficacy of anti-EGFR therapies in CRC, since KRAS mutant tumours do not respond to anti-EGFR agents." (PMID 25361007, 2014). "Another study with genetically engineered mice demonstrated that even though the compound, as single-agent, failed to inhibit murine KRAS-mutant lung tumors, when combined with a MEK inhibitor (ARRY-142886) resulted in tumor shrinkage." (PMID 24281308, 2012). "Among patients with KRAS wild-type tumours, the median OS was not reached for high AURKA-CN compared with 18.8 months for the group with low AURKA-CN tumours (HR=0.14, 95% CI: 0.038–0.514, P=0.003)." (PMID 22240781, 2012). "Our study extends the current paradigm to imply that patients with KRAS-, BRAF- or PIK3CA-mutant tumours may all derive limited benefit from treatment with EGFR mAb, and that BRAF mutations in particular account for a measurable fraction of patients whose KRASWT tumours do not respond to cetuximab." (PMID 19603024, 2009). "Remarkably, KRAS G12V; ACSS2 KO cells were not able to proliferate despite initial tumor formation." (PMID 40131933, 2025). "However, other studies detected only the KRAS G12V7–16 10-mer peptide and not KRAS G12V8–16 9-mer peptides from primary tumor tissues, natural HLA-A*11:01+ KRAS G12V+ Colo668 tumor cells, or HLA-A*11:01–engineered natural KRAS G12V+ SW620 tumor cells." (PMID 39846249, 2025). "However, it does not include the expression of biomarkers in the tumor, such as BRAF, KRAS, and CDX2, which often are strong prognosis indicators." (PMID 40943532, 2025). "We also did not have access to genetic information (KRAS, BRAF, and MSI), which may influence tumor responses to neoadjuvant treatment." (PMID 40715570, 2025). "However, upon DSS administration, multiple tumors formed in the distal colon tumors, and APC; KRAS mut mice developed small proximal colon tumors even without DSS treatment, with both tumor size and number increasing upon DSS administration." (PMID 41285904, 2025). "Moreover, CRP showed prognostic value for survival irrespective of tumour location and BRAF/KRAS status." (PMID 38613909, 2024). "MRTX1133, a non-covalent KRAS-G12D inhibitor developed in 2021, has shown promise in preclinical studies by inhibiting KRAS nucleotide exchange and RAF1 binding, reversing early PDAC growth, and positively altering the tumor microenvironment." (PMID 39457488, 2024). "However, the direct and indirect therapeutic targets of KRAS in CRC have not been identified; thus, elucidating the mechanisms and interactions between KRAS and the tumor microenvironment (TME) in-depth is paramount." (PMID 38481800, 2024). "Importantly, unlike KRAS mutant-specific inhibitors, SOS1 inhibition and MEK inhibition in our study is not limited to targeting KRAS pathway only in tumor cells." (PMID 38727236, 2024). "In an orthotopic KRAS mutant MIA PaCa-2 cell-derived xenograft mouse model, the pH-responsive micelles promoted a higher inhibition of the tumor growth and induced the apoptosis of tumor cells to a higher extent than the non-responsive system." (PMID 37376135, 2023).
tumor (continued). "Similarly, in the C1142 (KRAS G12V) PDX model, the combination of dasatinib and trametinib did not produce significantly greater tumor growth inhibition than did dasatinib or trametinib alone." (PMID 36952536, 2023). "Erlotinib (EGFR inhibitor), afatinib (pan-HER inhibitor), and BGJ398 (FGFR inhibitor) showed enhanced anti-tumor effects relative to the monotherapy of ARS-1620, due to their abilities to increase GDP-bound KRAS levels as well as combat negative feedback reactivation of RTKs." (PMID 37925476, 2023). "We found that the average nucleus size of proliferating cells was dramatically increased in LAs (Normal, 7.64 ± 0.04 μm, EGFR, 11.4 ± 0.12 μm, KRAS, 11.1 ± 0.12 μm error SEM, p = 2.5 x 10−69), suggesting that these enlarged cells are not senescent but are contributing to tumor growth." (PMID 36201559, 2022). "Consistently with these observations, co-treatment with adagrasib and anti- PD-1 demonstrated complete and prolonged response in vivo, without tumor regrowth after tumor cell inoculation, and increased PFS in KRAS G12C genetically engineered mouse models, compared with single-agent monotherapy." (PMID 35251972, 2022). "Prostratin inhibits KRAS and HRAS tumor growth by suppressing non-canonical Wnt/Ca2+ signaling." (PMID 35409064, 2022). "However, this does not agree with growing literature on KRAS and BRAF mutant tumors demonstrating rather it is the mitigation of ROS that benefits tumor growth in this context." (PMID 36253360, 2022). "Concurrent mutations in EGFR or ERBB2 and KRAS are not selected for and may be considered redundant in tumor cells, thus selective pressures may account for the mutual exclusivity of EGFR/ERBB2 and KRAS." (PMID 34204917, 2021). "BKA-073 potently suppresses tumor growth without significant normal tissue toxicity in small cell lung cancer (SCLC) and NSCLC xenografts, patient-derived xenografts, and genetically engineered mouse models of mutant KRAS-driven cancer." (PMID 34373755, 2021). "However, oncogenic activation of KRAS alone is not sufficient to drive tumour initiation; mouse models of PDAC in which KRAS is activated in the acinar compartment have shown that chronic inflammation is also required." (PMID 32571902, 2020). "Interestingly, viability of HAP1 cells did not seem to be affected by the knockout of known tumor type-specific oncogenes such as BCR, PIK3CA, KRAS, CTNNB1, or BRAF." (PMID 33228647, 2020). "In contrast, in H1299 tumours, 20 days after treatment, we detected a decrease of phosphorylation of MEK and ERK kinases in tumours expressing the pan-RAS degrader and not the KRAS degrader." (PMID 32591521, 2020). "Tumor growth of an inflammatory cell line in mouse-xenograft models was inhibited by MEK162 and neratinib as single agents, however, the combination of MEK162 plus neratinib was more efficacious, synergistic, and independent of KRAS status." (PMID 30118499, 2018). "However, TNF likely originates from tumor cells in MPE9 and non-specifically triggers NF-κB activation in any tumor type irrespective of its KRAS status and MPE competence, suggesting it functions as an autocrine growth factor across tumor types." (PMID 29445180, 2018). "This may be due to a detection limit of the KRAS assay, or the cytological “positive” CTC were not tumor derived." (PMID 28674438, 2017). "KRAS-activated PRKCD promotes growth, invasion, and migration of cancer cells, through MAPK signalling in NSCLC cell lines (and mouse model), whereas PRKCD activation in cells without active KRAS leads to tumour suppression." (PMID 29062084, 2017).
tumor (continued). "This is contrary to a previous report in non-small cell lung cancer, where the RAF proto-oncogene serine/threonine protein kinase was reported to be essential for KRAS driven adenocarcinoma of the lung rather than PDK1, the absence of which did not reduce tumor formation." (PMID 27845911, 2017). "Mutations affecting specific codons (so-called “hot-spot” codons) in exons 2, 3 and 4 of the KRAS and NRAS genes have been identified, which predict non-response to anti-EGFR mAbs and allow the further malignant proliferation of tumour cells, despite treatment." (PMID 27784278, 2016). "A female showed ALK rearrangement in the primary tumor (17 % break-apart signals) on FISH, but was negative in the metastatic brain tumor (FISH: 1 %); interestingly, KRAS testing led to the opposite result: detection of the G12C mutation in the metastatic but not in the primary lesion." (PMID 26968843, 2016). "This is a retrospective study, and alterations in other kinases such as KRAS, BRAF, and cMET that drive tumor growth were not investigated in this study; thus it is possible that the survival and response were affected, at least in part, by those underlying biomarkers." (PMID 23557218, 2013). "Our current study also reported relapse- and disease-free survival to be independent of gender, age, tumour location within the rectum, type of surgery, pathological T or N status and TRG, although, as for the KRAS analysis, the numbers of patients involved in the analysis are small." (PMID 23077464, 2012). "Our previous analyses of pAKT levels in a large panel of KRAS mutant PDAC cells lines found infrequent AKT activation, suggesting that this effector pathway is not consistently activated by Ras activation in this tumor type." (PMID 21044336, 2010). "Accumulating clinical evidence reveals that CRC is not solely a glycolytic tumor, but rather demonstrates increased expression of OXPHOS-related enzymes that drive invasion and metastasis in advanced stages, particularly in microsatellite-stable and KRAS-mutant subtypes." (PMID 41315223, 2025). "Additionally, genetic status data (KRAS, BRAF, and microsatellite instability), which may play an important role in the prognosis of the neoplasm, were not analyzed." (PMID 40560518, 2025). "In addition, the KRAS-driven non-classical Gln metabolic pathway proceeds through arginine methylase 1 (CARM1)-mediated MDH1 methylation, which is inhibited to regulate oxidative stress and ultimately to meet the changing metabolic demands of tumor cells." (PMID 40356913, 2025). "However, we found no survival differences between the mutant and wild-type KRAS groups in this primarily non-metastatic LARC setting, which might have been a chance finding due to the limited number of patients with known tumor KRAS status." (PMID 31893287, 2020). "Thus, the reduced tumor growth of KRAS4AG12V tumors does not depend on low level of the transgene expression or insufficient activation of the PI3K-AKT and RAF-MEK-ERK downstream pathways by the activated KRAS protein." (PMID 26799184, 2016).
tumor (continued). "In conclusion, our study highlights a pivotal role for miR-543 as a tumor suppressor in the regulation of CRC cell proliferation and metastasis by targeting KRAS, MTA1 and HMGA2 and suggests that miR-543 may serve as a novel diagnostic and prognostic biomarker for CRC metastasis." (PMID 26968810, 2016). "With the Wilcoxon rank test we find genes such as MYC, CCNE1, KRAS, NDRG1, MLL4 and MTSS1 for which data set specific normal tissue expression may not be significantly different from all tumor samples but is variable between low and high copy number tumor samples." (PMID 22174824, 2011). "While no comprehensive data on secreted factors determined by KRAS or BRAF oncogenes are available in CRC, this might comprise a further molecular level of specificity determining both the distinct roles of KRAS and BRAF in tumor progression and therapy response." (PMID 26299805, 2015). "However, it is known that a percentage of KRAS or NRAS WT patients is not responsive to EGFR targeted therapy, leaving to hypothesize that additional mediators could be involved in the dysregulation of molecular mechanisms leading to tumor initiation and development." (PMID 29221448, 2017).